DLX3 (distal-less homeobox 3)
Description:
Transcriptional activator (By similarity). Activates transcription of GNRHR, via binding to the downstream activin regulatory element (DARE) in the gene promoter (By similarity).
Synonyms: AI4; TDO
Tractability: PROTAC: ubiquitination databases record sites on it.
Gene: Protein-coding gene on chromosome 17 (49,990,005 to 49,995,224, reverse strand). Ensembl gene ENSG00000064195.
Subcellular location: Nucleus; Cytoplasm
Subcellular location (Human Protein Atlas): Nucleoplasm; Cytosol
Gene Ontology:
Molecular function: DNA binding; protein binding; sequence-specific double-stranded DNA binding; DNA-binding transcription factor activity; DNA-binding transcription factor activity, RNA polymerase II-specific; RNA polymerase II cis-regulatory region sequence-specific DNA binding; transcription cis-regulatory region binding; chromatin binding; DNA-binding transcription activator activity, RNA polymerase II-specific
Biological process: embryonic skeletal system development; epithelial cell differentiation; positive regulation of transcription by RNA polymerase II; regulation of transcription by RNA polymerase II; BMP signaling pathway; gene expression; hair cell differentiation; hair cycle; hair follicle cell proliferation; hair follicle development; hair follicle morphogenesis; odontoblast differentiation; regulation of DNA-templated transcription; Wnt signaling pathway
Cellular component: chromatin; cytoplasm; nucleus
Genetic constraint (gnomAD): Loss-of-function variants: 9 observed, 28.08 expected, observed/expected ratio (o/e) 0.32, 90% interval 0.19 to 0.56. The upper end of that interval is the gene's LOEUF score, 0.56, which puts it in group 2 of 6, group 1 being the genes least tolerant of losing a copy. Missense variants: 313 observed, 390.26 expected, observed/expected ratio (o/e) 0.8, 90% interval 0.73 to 0.88. Synonymous variants: 154 observed, 175.69 expected, observed/expected ratio (o/e) 0.88, 90% interval 0.77 to 1.
Homologues: Orthologues: chimpanzee DLX3 (100% identical), macaque DLX3 (100% identical), pig DLX3 (100% identical), dog DLX3 (99% identical), rabbit DLX3 (99% identical), mouse Dlx3 (98% identical), rat Dlx3 (98% identical), guinea pig DLX3 (98% identical), zebrafish dlx3b (66% identical), tropical clawed frog dlx3 (61% identical), Drosophila melanogaster Dll (33% identical), Caenorhabditis elegans ceh-43 (30% identical). Paralogues in human: DLX5 (55% identical), DLX2 (49% identical), DLX1 (33% identical), DLX6 (33% identical), DLX4 (30% identical), NANOG (20% identical), NANOGP8 (20% identical), BSX (19% identical), VENTX (14% identical).
Diseases named in the same sentence as DLX3 in open-access papers:
DLX3 is named in the same sentence as 34 diseases in open-access papers, as found by Europe PMC text mining. Sharing a sentence is not in itself a finding about the gene and the disease. The quoted sentences say what the papers report.
tricho-dento-osseous syndrome (18 papers, 2014 to 2026). Tricho-dento-osseous dysplasia (TDO) belongs to the ectodermal dysplasias and is characterized by curly/kinky hair at birth, enamel hypoplasia with discolouration and molar taurodontism, increased overall bone mineral density (BMD) and increased thickness of the cortical bones of the skull. "TDO syndrome has been linked to a frameshift mutation (GGGG deletion in DLX3 gene) just downstream of the Dlx3-HD." (PMID 36012753, 2022). "It has also been reported that the R133P mutation in the L1 loop region of Dlx3-HD results in TDO syndrome." (PMID 36012753, 2022). "Naturally occurring mutations in DLX3 have been identified in human populations with TDO syndrome and other ectodermal diseases." (PMID 28515447, 2017). "The classical TDO syndrome is associated with a four-base deletion downstream of the homeodomain in the DLX3 coding region (c.571_574delGGGG)." (PMID 28515447, 2017). "Loss of Dlx3 leads to enhanced proliferation and delayed regression such as in Tricho-Dento-Osseous syndrome caused by Dlx3 mutations." (PMID 24451143, 2014). "The mutation of DLX3 on autosome leads to tricho-dento-osseous syndrome." (PMID 40574800, 2025). "This unique structural and dynamic feature of Dlx3-HD plays an important role in target DNA recognition, which might be associated with TDO syndrome." (PMID 36012753, 2022). "Our study suggested that this unique structural and dynamic feature of Dlx3-HD plays an important role in target DNA recognition, which might be associated with tricho-dento-osseous syndrome." (PMID 36012753, 2022). "Another odontoblasts-related phenotype was found in association with a 4-bp deletion mutation in the Distal-Less Homeobox 3 (Dlx3) gene, which is etiologic for most cases of Tricho-dento-osseous syndrome; a disorder characterized by abnormalities in the thickness and density of bones and teeth." (PMID 34222243, 2021). "Interestingly, the missense-type mutations in Dlx3-HD are also able to cause TDO syndrome." (PMID 36012753, 2022). "Mutation of the Distal-less homeobox 3 (DLX3) gene is responsible for the human tricho-dento-osseous syndrome (TDO; OMM 190320), which is characterized by abnormal hair, teeth and bone development." (PMID 32117623, 2020). "Tricho-Dento-Osseous syndrome (TDO syndrome), a rare genetic disease, has been demonstrated to be caused by mutation of DLx3, with curly hair, enamel hypoplasia, dentinogenesis imperfecta, and increased density of jaw and skull bones." (PMID 35529491, 2022). "DLX3 was not included in the panel of genes of interest as pathogenic variants in the gene cause dominantly inherited trichodento‐osseous syndrome." (PMID 40387305, 2026). "Key words:Tricho-dento-osseous syndrome, DLX3 gene, precocious eruption." (PMID 28298997, 2017). "For example, a 4-bp deletion of the DLX3 gene has been reported in families with tricho-dento-osseous syndrome (TDO), which is characterized by abnormalities involving hair, teeth, and bone development." (PMID 34203994, 2021). "Mutation of distal-less homeobox 3 (DLX3) is responsible for human tricho-dento-osseous syndrome (TDO) with amelogenesis imperfecta, indicating a crucial role of DLX3 in amelogenesis." (PMID 25815730, 2015). "The patients with the TDO syndrome, showing a marked increased bone mineral density (BMD) in endochondral and intramembranous bones, imply that DLX3 exerts an essential role in bone formation." (PMID 27924851, 2016). "Mutation of distal-less homeobox 3 (DLX3) gene, a member of the distal-less homeodomain family (DLX1-6), is responsible for a human autosomal-dominant disease, tricho-dento-osseous syndrome (TDO; OMIM 190320)." (PMID 25815730, 2015). "Interestingly, a naturally occurring DLX3 mutant that disrupts the carboxyl-terminal domain leading to tricho-dento-osseous syndrome in humans displayed activities indistinguishable from wild type DLX3 in this system." (PMID 28515447, 2017).
amelogenesis imperfecta (7 papers, 2015 to 2025). Amelogenesis imperfecta (AI) represents a group of developmental conditions affecting the structure and clinical appearance of the enamel of all or nearly all the teeth in a more or less equal manner, and which may be associated with morphologic or biochemical changes elsewhere in the body. "Distal-Less Homeobox 3 (DLX3), a critical factor in tooth amelogenesis, is considered to be responsible for the development of amelogenesis imperfecta in humans." (PMID 38945953, 2024). "Variants in DLX3 cause tricho‐dento‐osseous syndrome (TDO, MIM #190320), a systemic condition with hair, nail and bony changes, taurodontism and amelogenesis imperfecta (AI), inherited in an autosomal dominant fashion." (PMID 30095208, 2019). "Mutations in AMELX, DLX3, LAMA3, LAMB3, and WDR72 were reported in both non-syndromic and syndromic amelogenesis imperfecta." (PMID 33672174, 2021).
dental caries (6 papers, 2021 to 2024). The decay of a tooth, in which it becomes softened, discolored, and/or porous. "Possible association of DLX3 gene (rs11656951 and rs2278163) polymorphisms with dental caries risk was assessed using the chi-squared test." (PMID 39400082, 2024). "For the DLX3 gene, a certain association was demonstrated between the rs2278163 polymorphism and the occurrence of dental caries in children with higher loads of Streptococcus mutans and Streptococcus sobrinus." (PMID 35336820, 2022). "Additionally, a weak correlation was found between the incidence of alleles in DLX3 rs10459948, localized near rs2278163, and a susceptibility to dental caries in children with higher loads of Streptococcus mutans." (PMID 35336820, 2022). "In summary, this study found multiple associations near genes that may play important roles in dental caries, such as TAS2R38, TAS2R3, TAS2R4, TASR25, DLX3 and DLX4, several of which have plausible biological functions relevant to tooth development and cariogenesis." (PMID 34311721, 2021). "These lines of evidence suggest that both DLX3 and DLX4 may play important roles in the dental caries process by the regulation tooth development." (PMID 34311721, 2021). "Both distal-less homeobox 3 (DLX3), which plays a role in odontogenesis, and DLX4, which is highly expressed in human dental pulp cells (DPC), might play an important role in the process of dental caries by regulating tooth development." (PMID 37275173, 2023).
acute lymphoblastic leukemia (2 papers, 2017 to 2020). Leukemia with an acute onset, characterized by the presence of lymphoblasts in the bone marrow and the peripheral blood. "As for DLX3/DLX4, studies have reported that reduced DLX3 expression was mediated by DNA hypermethylation at its promoter region in MLL‐AF4 childhood acute lymphoblastic leukemia." (PMID 32508046, 2020).
alopecia (2 papers, 2019 to 2022). Hair loss usually from the scalp. "Mutation in Dlx3 causes alopecia due to hair shaft differentiation failure." (PMID 31256073, 2019).
breast cancer (2 papers, 2010 to 2011). A primary or metastatic malignant neoplasm involving the breast. "Dlx-2 has been shown to be expressed at higher levels in human breast cancers compared to other Dlx genes, including Dlx-1, Dlx-3, Dlx-4, and Dlx-6, although its precise roles in tumor biology are not clear." (PMID 21917150, 2011). "In mammary tumors, the expression levels of DLX1, DLX3, DLX4 and DLX6 did not significantly differ from those observed in normal tissue (data not shown)." (PMID 21108812, 2010).
placental insufficiency (2 papers, 2017 to 2019). Failure of the placenta to deliver an adequate supply of nutrients and oxygen to the fetus. "In the present study, we sought to use the Dlx3+/− mouse model of placental insufficiency to investigate the effects of maternal choline supplementation on biomarkers of placental function and development across gestation." (PMID 30759768, 2019). "Most important to this body of work is the evidence supporting a role of DLX3 in human placental insufficiency." (PMID 30759768, 2019). "The present study was undertaken to investigate the effects of MCS on the determinants and parameters of fetal growth in the Dlx3 murine model of placental insufficiency." (PMID 28718809, 2017). "Herein, we investigated the effects of maternal choline supplementation (MCS) on parameters of fetal growth in a Dlx3+/− (distal-less homeobox 3) mouse model of placental insufficiency." (PMID 28718809, 2017). "In this study, we show for the first time that maternal choline supplementation modulates fetal growth in a model of placental insufficiency, the Dlx3+/− mouse." (PMID 28718809, 2017). "Since Dlx3+/− has been reported to be a model of placental insufficiency, we sought to determine whether MCS could improve placental efficiency as well as fetal growth." (PMID 28718809, 2017).
ankylosis (1 paper, 2022). Fixation and immobility of a joint. "Both miR-9-5p and Dlx3 can regulate osteogenic differentiation and myogenic differentiation, and they may be novel research objects of ossification of muscle, which causes ankylosis after burn or trauma." (PMID 35529491, 2022).
Anxiety (1 paper, 2021). Intense feelings of nervousness, tension, or panic often arise in response to interpersonal stresses. "Several anxiety-associated genes had direct interactions with striatal development genes, such as PRKCA with ADCY5 and DLX3, and ESR1 with ISL1." (PMID 34526518, 2021).
autism (1 paper, 2016). Persistent deficits in social interaction and communication and interaction as well as a markedly restricted repertoire of activity and interest as well as repetitive patterns of behavior. "We analyzed the Simons Simplex Collection of 2508 parent-offspring autism trios using VARPRISM, replicating 44 genes previously implicated in autism susceptibility and identifying 20 additional candidate genes, including MYO1E, KCND3, PDCD1, DLX3, and TSPAN4 (false discovery rate < 0.3)." (PMID 27562213, 2016).
COVID-19 (1 paper, 2023). A disease caused by infection with severe acute respiratory syndrome coronavirus 2. "By conducting SMR and HEIDI methods, several non-MHC region SNPs were identified as common shared genetic loci including rs143334143 (TCF19), rs2277732 (DPP9), rs77534576 (DLX3), and rs13081151 (FLT1P1), among others, which were significantly associated with OA-critical COVID-19 combined trait." (PMID 37398645, 2023).
fluorosis (1 paper, 2025). "Within this subset, polymorphisms in DLX3 (rs2278163) and ESR1 (rs12154178) are associated with fluorosis severity, indicating a role in modulating the phenotypic expression of enamel defects." (PMID 41174690, 2025). "Under the codominant model, individuals with the A/G genotype of DLX3 rs2278163 were significantly less likely to present moderate fluorosis compared to those with mild fluorosis (OR = 0.00, 95% CI: 0.00–NA; p = 0.028)." (PMID 41174690, 2025). "The universal presence of fluorosis in this cohort, coupled with the limited number of severe cases and the identification of potentially protective genotypes in DLX3 and ESR1, suggests that genetic variation plays a meaningful role in modulating individual susceptibility." (PMID 41174690, 2025). "Indeed, our results revealed polymorphisms in DLX3 and ESR1 that were more common in individuals with mild fluorosis, suggesting that these SNPs may act as protective factors, reducing the likelihood of severe enamel alteration even in the context of elevated fluoride exposure." (PMID 41174690, 2025).
glioma (1 paper, 2020). A benign or malignant brain and spinal cord tumor that arises from glial cells (astrocytes, oligodendrocytes, ependymal cells). "(A) Chromatin landscape around the DLX3 gene for H3K27me3, H3K4me2, and Polycomb components in glioma cell lines." (PMID 32902381, 2020).
osteoporosis (1 paper, 2021). A condition of reduced bone mass, with decreased cortical thickness and a decrease in the number and size of the trabeculae of cancellous bone (but normal chemical composition), resulting in increased fracture incidence. "Altogether, the miR-4739/DLX3 axis modulates the capacity of BMSCs to differentiate into osteoblasts, which potentially plays a role in osteoporosis pathogenesis." (PMID 34925225, 2021). "Altogether, the miR-4739/DLX3 axis modulates the capacity of BMSCs to differentiate into osteoblasts, which are potentially involved in osteoporosis pathogenesis." (PMID 34925225, 2021).
preeclampsia (1 paper, 2019). Preeclampsia is a hypertensive disorder of pregnancy that is characterized by new-onset hypertension with proteinuria presenting after 20 weeks of gestation, and depending on mild or severe forms may initially present with severe headache, visual disturbances, and hyperreflexia. "Because altered levels of pro-angiogenic factors have been implicated in the development of preeclampsia and other pregnancy disorders, we measured mRNA expression of several key modulators of placental angiogenesis throughout pregnancy in Dlx3+/− placentas." (PMID 30759768, 2019).
squamous cell carcinoma of the (1 paper, 2025). "The homeobox transcription regulator DLX3 is known for regulating skin epidermal homeostasis, and its loss induces squamous cell carcinoma of the skin." (PMID 40574800, 2025).
squamous cell carcinoma of the skin (1 paper, 2025). "In our study, we found that DLX3 was a risk factor for PC, not a protective factor as observed in squamous cell carcinoma of the skin." (PMID 40574800, 2025).
autosomal dominant disease (2 papers, 2015 to 2024). Autosomal dominant form of disease. "Tricho-dento-osseous (TDO) syndrome is a rare autosomal dominant disease resulting from distal-less homeobox 3 (DLX3) mutation." (PMID 38481875, 2024).
genetic disease (2 papers, 2016 to 2022). "Our findings in the rare human genetic disease unravel a novel mechanism of DLX3 involving the senescence regulation of bone formation." (PMID 27924851, 2016).
skin (2 papers, 2011 to 2019).
cancer (1 paper, 2018). A tumor composed of atypical neoplastic, often pleomorphic cells that invade other tissues. "Levels of MFNG in this subgroup of tumors also determined the transcriptional status of several Notch target genes such as NKD1, DLX3, EREG, EPHA4, or IL7R, known to be relevant for cancer progression." (PMID 30065304, 2018).
DLX3 also shares sentences with these, for which no sentence is quoted: taurodontism (3 papers); ectodermal dysplasia (2); osteogenesis imperfecta (2); atopic dermatitis (1); dentinogenesis imperfecta (1); Down syndrome (1); endometriosis (1); Intellectual disability (1); Osteopenia (1); pregnancy disorder (1); thyroid cancer (1); Torg-Winchester syndrome (1); trisomy 21 (1).